HIF1A (hypoxia inducible factor 1 subunit alpha)
Diseases named in the same sentence as HIF1A in open-access papers (continued):
Sharing a sentence is not in itself a finding about the gene and the disease.
prostate carcinoma (continued). "Our results suggested that determined common hsa-miR-494-3p, hsa-miR-3128, hsa-miR-8084 and their target HIF1A, AVRP1A, NHS, INSL4 may play a crucial role in therapeutic and early diagnostic strategies for prostate cancer." (PMID 36326314, 2022). "Additionally to MMP9, SENP1 regulated the expression of MMP2 through the HIF-1α signaling pathway in prostate cancer." (PMID 33923236, 2021). "In hypoxic PC-3 cells (prostate cancer cells), melatonin could reduce HIF-1α accumulation by inactivation of SPHK1 (new modulator of HIF-1α)." (PMID 33923028, 2021). "Moreover, PI3K/AKT pathway and expression of HIF-1α, VEGF, PDGF-A, and PDGF-B are activated by KLF5 loss and blocked by KLF5 overexpression in PTEN-deficient prostate cancer." (PMID 33493334, 2021). "A recent study showed that NOX expression is directly associated with prostate cancer in mice, and when NOX was inhibited, the expression of HIF-1α in the nucleus was significantly decreased as well as a reduction in the proliferation and colony formation of prostate cancer." (PMID 34336107, 2021). "Contrary to the finding in the current study that Septin4 can promote apoptosis by reducing HIF-1α levels in cardiomyocytes, it has been reported that other proteins in the Septin family like Septin9, can promote tumorigenesis by stabilizing HIF-1α levels in human prostate cancer cells." (PMID 34230460, 2021). "For example, NO-sulindac can reduce the tolerance of prostate cancer to chemotherapy under hypoxic conditions by inhibiting HIF-1α, which can be used to exploit a better treatment by increasing the sensitivity of hypoxic cells to chemotherapy and radiation therapy." (PMID 34356634, 2021). "Mechanistically, SENP1 overexpression was associated with the increased expression of several transcription factors essential for the development and progression of prostate cancer, such as androgen receptor (AR) and HIF-1α, which is critical for neoangiogenesis." (PMID 33923236, 2021). "Moreover, this compound revealed the positive effect on prostate cancer by the inhibition of HIF-1α-mediated androgen receptor signaling and reducing proliferation of prostate cancer in vitro and in vivo." (PMID 34948455, 2021). "Furthermore, the WNT/β-catenin signaling pathway drives post-radiotherapy progression in xenograft models of prostate cancer cells overexpressing HIF-1α." (PMID 34539584, 2021). "In addition, primary cancer cells can also secrete exosomes to deliver pyruvate kinase M2 to bone marrow stromal cells (BMSCs) and upregulate CXCL12 of BMSCs in a HIF-1α-dependent manner, forming a premetastatic niche for bone metastasis of prostate cancer." (PMID 33926551, 2021). "Recently, it was reported that hypoxia stimulus increased Annexin A1 protein expression, and thus to accelerate cell invasion and aggressiveness of prostate cancer cell, implying that HIF-1α/Annexin A1 signaling played a crucial role in hypoxia-regulated metastasis of prostate cancer." (PMID 32215176, 2020). "Additionally, TRPM8 reduces RACK1-mediated ubiquitination of HIF-1α to elevate HIF-1α expression during the hypoxic growth adaptation of prostate cancer cells." (PMID 33344232, 2020). "The results indicated that HIF1a can bind to the corresponding region in prostate cancer cells." (PMID 33110365, 2020). "Thus, we determined if Annexin A1 expression was affected by HIF-1α in androgen-independent prostate cancer cells." (PMID 32215176, 2020). "By contrast, propofol was reported to reduce HIF-1α expression in prostate cancer cells." (PMID 32437450, 2020).
prostate carcinoma (continued). "Moreover, we uncovered that HIF‐1α is a key transcription factor responsible for inducing PRKAR2B expression in prostate cancer." (PMID 33025691, 2020). "Collectively, these findings suggest that PRKAR2B might promote glycolysis by regulating HIF‐1α in prostate cancer." (PMID 33025691, 2020). "HIF-1α may also act on some EMT transcription factors indirectly through FoxM1 signaling pathway in prostate cancer cell lines and through PAFAH1B2 gene in pancreatic cancer." (PMID 32322559, 2020). "Importantly, HIF‐1α expression has been demonstrated to increase as prostate cancer progressed from androgen‐dependent to androgen‐independent states." (PMID 33025691, 2020). "The study delivers new data on PSMD4 regulation by HIF1a in the prostate cancer cell line." (PMID 33110365, 2020). "The downstream target of HIF-1α contributing to the hypoxic adaptation of prostate cancer cells remains unclear." (PMID 32215176, 2020). "It has been suggested that the activation of AR in hypoxic conditions is HIF-1α mediated, hence targeting HIF-1α could influence the AR stimulatory effect of hypoxia in castration-resistant prostate cancer." (PMID 31151317, 2019). "The protective role of sulforaphane and capsaicin on prostate cancer may rely on mechanisms involving the inhibition of Tip60, AR and HIF-1α effects." (PMID 31671779, 2019). "Overexpression of HIF1α in PC-3 prostate cancer cells xenografts could increase tumor size and upregulate ATG5 expression." (PMID 31700698, 2019). "In addition, sulforaphane has been shown to inhibit HIF-1α expression induced by hypoxia and to decrease glycolysis in in vitro models of castrate-resistant prostate cancer." (PMID 31671779, 2019). "Although we had determined that propofol could reverse hypoxia-induced EMT in prostate cancer cells, it was unclear whether the effect of propofol was related to HIF-1α." (PMID 29568752, 2018). "We therefore asked whether V-ATPase inhibitors affect HIF-1α expression and stability in prostate cancer cells and whether HIF-1α may link V-ATPase and AR." (PMID 29988966, 2018). "We hypothesized that propofol affects hypoxia-induced docetaxel resistance in prostate cancer cells by regulating HIF-1α." (PMID 29568752, 2018). "However, our studies are the first to link the V-ATPase-HIF-1α axis specifically to AR levels in prostate cancer." (PMID 29988966, 2018). "Previous study showed the expression of EZH2 could be regulated by HIF-1α/HIF-1β dependent hypoxic pathway in prostate cancer." (PMID 29699590, 2018). "Taken together, our findings demonstrate that propofol plays an important role in hypoxia-induced docetaxel sensitivity and EMT in prostate cancer cells and that it is a potential drug for overcoming drug resistance in prostate cancer cells via HIF-1α suppression." (PMID 29568752, 2018). "We transfected HIF-1α siRNA into prostate cancer cells to knock down HIF-1α expression and found that hypoxia-induced docetaxel resistance disappeared and that propofol did not reverse docetaxel resistance in prostate cancer cells after HIF-1α siRNA transfection." (PMID 29568752, 2018). "In this study, we found that propofol could reverse hypoxia-induced docetaxel resistance in prostate cancer cells by reversing EMT via HIF-1α inhibition." (PMID 29568752, 2018). "Our results suggest that atorvastatin could enhance radiosensitivity of prostate cancer cells through inhibiting HIF-1α protein level." (PMID 28760843, 2017). "Although HIF1A rs11549465 polymorphism showed a tendency of increasing the risk of prostate cancer, no statistical significance was detected under any genetic models." (PMID 28415653, 2017). "In addition, due to deletion of PTEN that represents one of the most frequent prostate cancer genetic alteration, prostate tumorigenesis is promoted by BMI-1-mediated repression of ER-β that enables the HIF-1α/VEGF signaling altered in PCa cells." (PMID 28430640, 2017).
prostate carcinoma (continued). "Atorvastatin could enhance radiosensitivity in hypoxia-induced prostate cancer cells, which may be related with inhibition of HIF-1α protein." (PMID 28760843, 2017). "In the current study, we found a trend for higher HIF-1α protein expression in prostate carcinomas compared to nodular prostate hyperplasia, which may be explained by the limited samples analysed." (PMID 28143503, 2017). "Interestingly, ER-β2 and ER-β5 variants, which have tumor-promoting actions, are able to stabilize HIF-1α and allow the expression of hypoxic genes in prostate cancer." (PMID 28430640, 2017). "Further, the results of our experiments in starved and hypoxic conditions encouraged us to test whether FQ could interfere with expression/stabilization of hypoxia-inducible factor-1α (HIF-1α) in prostate cancer cells." (PMID 29162859, 2017). "A previous study found that hypoxia following irradiation could enhance radioresistance of prostate cancer cells through up-regulating HIF-1α." (PMID 28760843, 2017). "Since HIF-1α may promote radioresistance of prostate cancer, we further investigate the effect of atorvastatin on radiosensitivity of prostate cancer cells." (PMID 28760843, 2017). "In conclusion, atorvastatin could enhance radiosensitivity of hypoxia-induced prostate cancer cells, which may be related with inhibition of HIF-1α protein." (PMID 28760843, 2017). "HIF-1a overexpression under normoxia could serve as a biomarker for chemoresistance, radioresistance and castration resistance in prostate cancer." (PMID 29069829, 2017). "The hypoxia inducible factor 1-alpha (HIF1A) gene has been suggested to play a critical role in cancer progression, and the relationship between HIF1A rs11549465 polymorphism and risk of prostate cancer has been investigated in previous studies." (PMID 28415653, 2017). "Likewise, a greater expression of HIF-1α has been found in human prostate carcinomas compared to nodular prostate hyperplasia." (PMID 28143503, 2017). "Hypoxia could enhance radioresistance in prostate cancer cells through up-regulating HIF-1α, which could be inhibited by statins in several cancer cells." (PMID 28760843, 2017). "Interestingly, in our unpublished results on prostate cancer cells and melanoma, we determined a down-regulation of HIF-1α, after treatment with EFA-CLA." (PMID 27551323, 2016). "We have next investigated whether HIF-1α upregulation will affect prostate cancer cell proliferation, caspases activity and SK1 expression and activity." (PMID 27821815, 2016). "In addition, a binding of HIF-1α to the hypoxia-response element of the PDL-1 promoter has been shown in both breast and prostate cancer cell lines demonstrating a link of HIF-1α with the checkpoint inhibitor." (PMID 27044404, 2016). "Taking into consideration known ZFP91 functions, this could play a role in NF-κB and HIF-1α signaling in prostate cancer." (PMID 27975057, 2016). "Furthermore, we demonstrate that the expression of PHF8 is induced by hypoxia in prostate cancer cell lines and this induction requires HIF1α and HIF2α." (PMID 27991916, 2016). "This is the first evidence of mTOR-mediated regulation of HIF-1α in prostate cancer." (PMID 27821815, 2016). "The angiogenic pathway map presents the detail signaling circuitries of prostate cancer associated angiogenesis, including the activities of four distinct angiogenic switches (VEGF, HIF1A, HO-1 and CEACAM1), growth factor receptor signaling and the role of transcription factors." (PMID 27476486, 2016). "The observation that HIF-1α can be activated in response to inflammatory cytokines may suggest a role for a feedforward loop between prostatic inflammation and HIF-1α in human prostate cancers." (PMID 27058421, 2016). "As expected, the VEGF mRNA expression was increased after miR-182 mimics transfection, further suggesting that miR-182 could control HIF1α expression level in prostate cancer cells." (PMID 26205124, 2015).
prostate carcinoma (continued). "Since miR-183-96-182 is hypoxia-responsive under the regulation by HIF1α, whether miR-183-96-182 plays regulatory roles in hypoxia adaption or angiogenesis in prostate cancer was further explored." (PMID 26205124, 2015). "Upregulated HIF1-α in prostate cancer tissues as observed in the present study could likely to be responsible for induction of promoter hypermethylation and hsa-miR-155 mediated modulation of 3’UTR activity of hMLH1 and hMSH6 genes as detected by others." (PMID 25938433, 2015). "To assess whether an inverse correlation between ERβ and HIF-1α/IKKβ expression exists in prostate cancer, we compared their expression in Gleason grade 5 tumors and normal prostate epithelia by immunofluorescence staining." (PMID 26450901, 2015). "If our hypothesis is correct, we would expect to see the altered expression of PHD2 and FIH1 as well as HIF1α in the tumors derived from miR-182 overexpressing prostate cancer cells." (PMID 26205124, 2015). "Our data reveal that ERβ functions as a repressor of HIF-1α-mediated NF-kB activation and support the possibility that ERβ may contribute to the prevention of chronic inflammation in the prostate and prostate cancer." (PMID 26450901, 2015). "Meanwhile, the expression of miR-183-96-182 and HIF1α target gene VEGF, was increased in DU145 and PC-3 prostate cancer cells after HIF1α-DM transfection, indicating that HIF1α might regulate the transcription of miR-183-96-182." (PMID 26205124, 2015). "This feedback loop is capable of maintaining high levels of HIF-1α expression during hypoxia, and might also account for high levels of endogenous HIF-1α expression in PC-3 and other prostate cancer cell lines." (PMID 25821081, 2015). "MSeA may also be used in combination with chemotherapy agents for invasive and recurrent or resistant prostate cancers, which express high HIF-1α." (PMID 24515947, 2014). "Furthermore, it was found that nobiletin inhibited VEGF expression through regulating AKT/HIF-1α pathways in prostate cancer cell line PC-3." (PMID 25342300, 2014). "Furthermore, tumor reduction was found in nude mice implanted with human prostate cancer cells treated with the HIF-1α inhibitor EZN-2968." (PMID 25105148, 2014). "In the current study, we demonstrated for the first time that berberine could efficiently downregulate HIF-1α expression in hypoxic prostate cancer cells in vitro and in vivo." (PMID 24886405, 2014). "To further evaluate the clinical relevance of MAOA and HIF1A, we assessed whether elevated MAOA levels in prostate cancers treated with neoadjuvant chemotherapy associated with increased HIF1A in vivo." (PMID 25198178, 2014). "In summary, we showed that berberine at low concentrations substantially radiosensitized hypoxic prostate cancer cells by downregulating HIF-1α and VEGF expression, which may contribute to tumor aggressiveness, invasiveness and resistance to IR." (PMID 24886405, 2014). "In addition, Imatinib has been reported to reduce HIF1α protein expression in a model of prostate cancer by a hypoxia-independent process." (PMID 25243742, 2014). "We identify a nuclear interaction between ARRB1 and HIF1A in prostate cancer cells and demonstrate that ARRB1 is recruited to promoter regions of metabolic genes in a HIF1A-dependent manner where it contributes to metabolic genes expression as a co-regulator of HIF1A transcriptional activity." (PMID 24837709, 2014). "Taken together, these data indicate that directly inhibiting HIF-1 by targeting the HIF-1α/p300 interaction with these ETPs may prove valuable in suppressing tumor angiogenesis and prostate cancer progression." (PMID 24775564, 2014). "Paone and colleagues found that TLR3 could regulate the process of angiogenesis and apoptosis in prostate cancer cells through hypoxia-inducible factor 1α (HIF-1α) and PKC-dependent mechanism." (PMID 25101092, 2014). "HIF-1α over-expression has been identified in both prostate cancer tissue and cell lines." (PMID 23594994, 2013).
prostate carcinoma (continued). "Our results are consistent with observations demonstrating that PGE2 causes the stabilization of HIF-1α independent of hypoxia in PC-3 ML human prostate cancer cells, HCT116 human colon carcinoma cells and AGS gastric carcinoma cells." (PMID 23566437, 2013). "The current paradigm is that tumor hypoxia increases HIF1α expression in prostate cancer." (PMID 23342109, 2013). "Although over-expression of HIF-1α could be hypoxia-dependent, human prostate cancer cells can express functional HIF-1α protein excessively under normoxic conditions, the mechanisms of which remain largely unknown." (PMID 23594994, 2013). "Reduced miR-199b expression could contribute directly to elevated expression of HIF-1α in prostate cancer cells." (PMID 23594994, 2013). "Nevertheless, the antitumor mechanism of CT in association with HIF-1α and AEG-1 signaling in prostate cancers under hypoxia still remains unclear." (PMID 23243443, 2012). "Finally, HIF1α activity is increased in response to androgen signaling in androgen-sensitive prostate cancer cells." (PMID 22135748, 2011). "Thus, our findings suggest that BA can be a potent anti-angiogenic agent by targeting STAT3/HIF-1α/VEGF signaling for prostate cancer therapy." (PMID 21731766, 2011). "In this study we analysed the molecular mechanisms by which zinc downregulated HIF-1α levels and activity in prostate cancer and glioblastoma cells under hypoxia, whether constitutive or induced, and its biological relevance." (PMID 21179202, 2010). "Here we report that zinc downregulated HIF-1α protein levels in human prostate cancer and glioblastoma cells under hypoxia, whether induced or constitutive." (PMID 21179202, 2010). "The aim of this study was to elucidate whether the cytoplasmic stabilization of HIF1α in androgen independent NE differentiated prostate cancer is due to the presence of certain HIF1α isoforms." (PMID 20663134, 2010). "Furthermore, defining the regulatory axis consisting of Siah2 and HIF-1α/FoxA2 cooperation suggests novel therapeutic modalities to treat these most aggressive forms of prostate cancer." (PMID 21037926, 2010). "HIF1α variants with and without exon 14 (HIF1α14+ and 14-) were detected in all cases of benign prostate hyperplasia and prostate cancer." (PMID 20663134, 2010). "Induction might be triggered by stabilisation of hypoxia inducible factor-1α (HIF1α), as shown in prostate cancer model." (PMID 21102591, 2010). "Induction of HIF-1α protein and target gene expression by culture under hypoxic conditions has been described for a wide variety of human cancer cell lines, for example, colon, pancreas, breast and prostate cancer." (PMID 19223895, 2009). "Expression of the PHD proteins did not significantly associate with HIF-1α, consistent with studies in prostate cancer, but were also unexpectedly positively associated with HIF-2α." (PMID 19844231, 2009). "Moreover, it remains to be studied whether hypoxia-driven upregulation of CNPY2 (via HIF-1α) additionally modifies any of these post-translational events, creating a feedforward loop that further stabilizes AR in castration-resistant prostate cancer." (PMID 40001982, 2025). "This potential feedforward mechanism is particularly relevant because it is well known that androgen deprivation through castration can create a hypoxic environment in prostate cancer, leading to increased expression of HIF-1α, which in turn may activate CNPY2 expression." (PMID 40001982, 2025). "Further research revealed that under normal oxygen conditions, lactate may stabilize HIF1α through HIF1α lactylation in prostate cancer and subsequently modulate downstream pathways, demonstrating the many roles that lactate and lactylation play in carcinogenesis." (PMID 38983918, 2024).